RBM10 (RNA binding motif protein 10)
Diseases named in the same sentence as RBM10 in open-access papers (continued):
Sharing a sentence is not in itself a finding about the gene and the disease.
tumor (continued). "Recent studies indicated that RBM10 was involved in many tumours, highlighting its potential as a target for new therapeutics." (PMID 39636180, 2024). "It is closely related to ARM-level copy number alterations and HLA loss of heterozygosity, among other phenomena, which also shows that RBM10 is involved in the regulation of the tumor immune environment." (PMID 37509501, 2023). "As expected, the RBM10 was only focally positive with nuclear expression in up to 10% of tumor cells, despite having a stable expression on the mRNA level." (PMID 37469410, 2023). "Recent reports showed that knockdown of RBM10 in human cancer cells enhances cell proliferation, suggesting that RBM10 acts as a tumor suppressor (23, –25)." (PMID 38032932, 2023). "The median expression of RBM10 in different tumor types was taken as the cut-off value, and the tumors were categorized into high and low expression groups." (PMID 39282149, 2022). "To associate a radiographic response with a pathological response, we next followed a patient (case 3) treated with neoadjuvant osimertinib in a clinical trial (NCT03433469), whose tumor harbored the EGFRL858R and RBM10 Q595* co-occurring mutations." (PMID 35579943, 2022). "In our investigation, we first evaluated the RBM10 expression level in normal as well as tumor tissues of 33 cancers." (PMID 39282149, 2022). "These clinical data are consistent with most of our experimental findings showing that genetic inactivation of RBM10 limits the initial apoptotic response in EGFR-mutant tumor cells." (PMID 35579943, 2022). "Our findings indicate that RBM10 deficiency in EGFR-mutant LA tumors decreased the apoptotic response to EGFR inhibitor therapy, leading to tumor progression during EGFR TKI treatment and worse clinical outcomes." (PMID 35579943, 2022). "From this, we concluded that RBM10 regulated AS of Neat1, and the tumor-promoting effect of Neat1 was mainly attributed to Neat1_2." (PMID 36335386, 2022). "Consistently, the xenograft tumor model was also proved that upregulation of RBM10 significantly decreased tumor growth." (PMID 39282149, 2022). "KDM6A and RBM10 were more likely to have SNV in tumours derived of older patients in TCGA and AACR GENIE but were not recurrently mutated in PCAWG data and not analysed in that dataset." (PMID 35017538, 2022). "Following 2 months of neoadjuvant osimertinib treatment, we confirmed low tumor cell RBM10 expression and observed radiographic SD, with 80% tumor cell viability in the osimertinib-treated, resected tumor specimen upon clinical pathology assessment." (PMID 35579943, 2022). "Taken together, these results strongly indicate that RBM10 is involved in LUAD progression as a tumor suppressor." (PMID 34975322, 2022). "At the same time, we also found that the expression of RBM10 was different in different tumor stages and molecular subtypes of various tumor types, indicating that RBM10 was closely related to tumor progression and tumor molecular subtypes." (PMID 39282149, 2022). "So far, little is known about the correlation between RBM10 expression and tumor immune infiltration." (PMID 39282149, 2022). "Previous research by our group also found that RBM10 can regulate RAP1/AKT/CREB to play a tumor suppressor role." (PMID 36335386, 2022). "Specifically, in ACC and KICH, the RBM10 level gradually increased with the increase of tumor grades." (PMID 39282149, 2022). "RBM10 modulated mRNA alternative splicing of the mitochondrial apoptotic regulator Bcl-x to regulate tumor cell apoptosis during treatment." (PMID 35579943, 2022).
tumor (continued). "Patient L2 TB and CDX presented a KRAS-mutant tumor with concurring mutations in genes KEAP1, STK11, and RBM10." (PMID 35511434, 2022). "In the subcutaneous xenograft model, we observed that the tumor size in the H3255 RBM10-overexpression xenograft groups was significantly decreased compared with the control groups at the end of the experiment." (PMID 39282149, 2022). "We treated mice bearing H3255 or PC-9 tumor xenografts with osimertinib or vehicle and found that mice with tumors in which RBM10 was silenced had decreased osimertinib sensitivity compared with mice bearing shScr control–expressing tumors." (PMID 35579943, 2022). "The RBM10 expression was reduced in C6 subtype of 10 types of tumor excluding PRAD and TGCT but increased in C6 subtype of UCEC and TGCT." (PMID 39282149, 2022). "In summary, the present study revealed a first working model for how RBM10 inhibits LUAD tumor growth and metastasis." (PMID 34975322, 2022). "The methylation levels of RBM10 in various types of tumor tissues were analyzed by the GSCA database." (PMID 39282149, 2022). "Most current studies about the role of RBM10 in cancer have been focused on an individual or limited to some specific tumor types." (PMID 39282149, 2022). "Through a series of in vitro cytological assays including CCK-8, clone formation, and Transwell assays, we confirmed that RBM10 acted as a tumor suppressor gene and inhibited the growth, migration, and invasiveness of LUAD cells." (PMID 39282149, 2022). "We observed earlier initial tumor progression in mice bearing RBM10-KD tumors compared with controls in osimertinib-treated mice (Wilcoxon test P = 0.0002, n = 13/group)." (PMID 35579943, 2022). "The correlation of high expression of RBM10 in HCC with more advanced tumor stages was significantly positive." (PMID 39282149, 2022). "We identify 12 significantly mutated genes and 5 focal CNA regions, and demonstrate common mutations in post-transcriptional modification-related potential driver genes METTL14 and RBM10 in pCCA tumours." (PMID 35650238, 2022). "Our data suggest 1 model for the multifaceted evolution of resistance, such that RBM10 inactivation, for instance via subclonal mutation, may allow for a fraction of cancer cells to avoid apoptosis and persist during initial targeted therapy, resulting in an incomplete tumor response." (PMID 35579943, 2022). "In here, we also found that in most tumor types, the RBM10 expression was positively correlated with the T cell CD4+ Th1 cell infiltration level and negatively correlated with the T cell CD4+ Th2 cell infiltration level." (PMID 39282149, 2022). "To further investigate how immune activity was altered in RBM10 deficient patients, we first compared TMB, which is reported to correlate with anti-tumor immunity." (PMID 34367963, 2021). "As a tumor suppressor gene, RBM10 can reduce the malignant progression of HCC and is a novel prognostic biomarker and therapeutic target in patients with liver cancer." (PMID 33718153, 2021). "To uncover the ramifications of RBM10 deficiency, we performed whole exome sequencing (WES) in 39 tumor samples from early-stage LUADs presenting as GGNs." (PMID 34367963, 2021). "RBM10 is widely recognized as a tumor suppressor gene because it can inhibit tumor proliferation, promote apoptosis, and prevent metastasis." (PMID 33718153, 2021). "Its tumor suppression role is well supported by bioinformatics data, as the lower expression of RBM10 is correlated with lower survival rate of colorectal cancer patients." (PMID 32947864, 2020). "RBM10 (RNA-binding protein 10) is belongs to RNA binding proteins family and regards as a tumor promoter universally participate in tumorigenesis by influencing tumor proliferation and apoptosis." (PMID 32098099, 2020).
tumor (continued). "Initial functional studies have demonstrated that RNA‐binding motif protein 10 (RBM10) can promote apoptosis and suppress cell proliferation; however, the results of several studies suggest a tumour‐promoting role for RBM10." (PMID 30955253, 2019). "We observed that Dnmt3aR878H/+Npm1cA/+ MDS/MPD was associated with mutations in the tumor suppressor Cux1, previously shown to drive MDS and MDS/MPD and in the RNA splicing genes Rbm10 and U2af2." (PMID 30692594, 2019). "Very recently, however, contradictory results have emerged, suggesting a tumor promoter role for RBM10." (PMID 29274279, 2018). "RBM10's cellular functions are beginning to be explored, with initial studies demonstrating a tumor suppressor role." (PMID 29274279, 2018). "Three recent gene expression studies involving various tumor types provide in vivo data supporting the suggestion that RBM10 promotes transformation in systems where RBM5 is downregulated." (PMID 29274279, 2018). "Since RBM10 is a tumour suppressor, and the regulation of alternative splicing is an important process that is deregulated in cancer, we set out to identify novel RBM10-regulated alternative splicing events using cancer cell lines." (PMID 28728573, 2017). "As described in our study, the mutational architecture and corresponding patterns of RNA expression revealed by integrative data analysis support a role of RBM10 as a tumor suppressor in LUAD." (PMID 28091594, 2017). "RBM5 and RBM10 also share functional similarities, and both have tumor-suppressor properties in various cancer cell lines." (PMID 28662214, 2017). "Expression of RBM10 is also important for tumor suppression, and reduced expression has been observed in pancreatic cancer and non-small cell lung carcinoma." (PMID 28728573, 2017). "Mutations in various splicing regulatory factors such as U2AF1, ZRSR2, SRSF2, SF3B1, and RBM10 have been described in multiple tumor types." (PMID 28105922, 2016). "RNA binding motif protein 10 (RBM10) is a tumor suppressor involved in alternative splicing." (PMID 40069781, 2025). "These mutations lead to reduced RBM10 expression in LUAD, and this decrease is significantly higher in patients with stage IV LUAD than in those with stage I–III LUAD, suggesting a role for RBM10 in tumor metastasis." (PMID 40069781, 2025). "Given that deleting the splicing regulator Rbm10 in LKB1-deficient mice had a moderate tumor suppressing effect,153LKB1 splicing may prove to be a suitable target to antagonize tumor cell survival." (PMID 39735555, 2025). "Given the previously reported tumor suppressive role of RBM10 in LUAD, we proceeded to interrogate whether RAC1B contributes to the RBM10 function." (PMID 40548642, 2025). "Yet, it remains unknown whether cancer-derived mutant RBM10 compromises its tumor suppression function and, if so, the molecular insight of the underlying mechanisms." (PMID 38032932, 2023). "Hence, identification of RBM10 in our present study as another regulator of c-Myc by partnering with uL18 and uL5 would unveil a function of this tumor suppressor." (PMID 38032932, 2023). "It seemed that ACVR2A, FANCA, RBM10, and SPTA1 mutations might have important functions in tumour development for different subtypes and different molecular characteristics in Chinese patients." (PMID 38024139, 2023).
tumor (continued). "Our analysis also yielded RBM10 and FBXW7 as frequently mutated genes in metastatic ccRCC tumours." (PMID 35231161, 2022). "More importantly, pathway enrichment analysis suggested that multiple signaling pathways might participate in the tumor-promoting mechanism of silencing RBM10, such as the Wnt/β-catenin pathway, NF-KB pathway, TGF-β pathway." (PMID 34975322, 2022). "Taken together, based on these data, we speculate that the high RBM10 expression inhibited tumor progression via blocking immune escape by reducing M2 macrophages in some tumors." (PMID 39282149, 2022). "Thus, at the individual patient level, across multiple cases, RBM10 inactivation was associated with decreased initial EGFR TKI sensitivity, relatively early clinical progression, and a decreased pathological tumor response in EGFR-mutant LA." (PMID 35579943, 2022). "These pieces of evidence suggest that RBM10 mainly acts as a tumor suppressor in LUAD." (PMID 39282149, 2022). "We confirmed that tumor growth was not impacted by RBM10 loss using H3255 and PC-9 RBM10 CRISPR-KO cells implanted and grown in vivo for over 2 months." (PMID 35579943, 2022). "Therefore, new drugs targeting RBM10 in tumor-infiltrating immune cells can be developed in the future, which will bring good news to the immunotherapy of tumor patients." (PMID 39282149, 2022). "It is worth mentioning that RBM10, KEAP1 and LRP1B, regarded as tumor suppressor genes, were more frequently mutated in aged group compared with young group, which may contribute to the high incidence of LUAD in the elderly." (PMID 35371328, 2022). "Therefore, further research exploring the role and potential molecular mechanism of RBM10 methylation in different tumor progressions is necessary." (PMID 39282149, 2022). "Moreover, our recent study has also proved the potential of RBM10 as a tumor suppressor that has the ability to inhibit the metastasis and proliferation of LUAD by partially inactivating the Wnt/β-catenin pathway." (PMID 39282149, 2022). "Similarly, PD-L1 protein level was lower in tumor tissues generated by RBM10 overexpression cells than vector control based on IHC and WB." (PMID 39282149, 2022). "Furthermore, tumor suppressor genes with a mutational frequency of >10% in cell lines involved SMAD4, SMARCA4, ARID1A, ARID2, and RBM10." (PMID 36013219, 2022). "In conclusion, although RBM10 has different or even opposite prognostic value in different tumors, all these data strongly lead to the suggestion that it can be used as a biomarker for prognostic prediction of tumor patients." (PMID 39282149, 2022). "The predominantly metastatic tumours in our cohort contained more frequent mutations in several genes such as SETD2, APC, KDM5C, HIF1A, RBM10, TRAK1 and FBXW7, while we detected lower mutation rates in VHL compared to the primary tumours analysed in the TCGA study." (PMID 35231161, 2022). "Furthermore, RBM10 was recently reported to be a tumor suppressor that can promote tumor cell apoptosis and inhibit colonization." (PMID 33718153, 2021). "In this review, we summarize the role of RBM10 in majority of tumor tissues and cells studied so far, and we look forward to its future clinical value in the design of new-targeted drugs that regulate upstream and downstream pathways and would improve prognosis prediction." (PMID 33718153, 2021).
tumor (continued). "RBM10 regulates many gene pathways involving in the tumor development or progression, such as focal adhesion, peroxisome proliferator-activated receptor-regulated gene pathway, cytokine-cytokine receptor interaction, mitogen-activated protein kinase signaling, complement and coagulation cascades." (PMID 34804951, 2021). "Additionally, the RBM10 gene knockdown promotes cell proliferation in vitro, while the accumulation and stable overexpression of RBM10 in BALB/C nude mice significantly inhibited tumor growth." (PMID 33718153, 2021). "In tumor tissues, the upregulation of RBM10 and RBM5 may occur due to increased translation and protein stability, resulting in a significant increase in protein content, especially if RNA content remains unchanged or decreased." (PMID 33718153, 2021). "The tumor mutation load showed BCL6 corepressor like 1 (BCORL1) and a-raf proto-oncogene (ARAF) have the highest copy number amplification, whereas lysine demethylase 6A (KDM6A) and RNA binding motif protein 10 (RBM10) showed the highest copy number deletion." (PMID 33629637, 2021). "Although we know that RBM10 may act as a tumor suppressor, it not only promotes apoptosis and inhibits proliferation but is also related to cell invasion and metastasis because it can reduce glycolysis, EMT, and angiogenesis." (PMID 33718153, 2021). "The c-Src family tyrosine kinases can phosphorylate RBM10, and the phosphorylated RBM molecules are reportedly upregulated in tumor tissues, which may affect the localization and function of RBM10." (PMID 33718153, 2021). "RBM10 decreased the tumor cell proliferation, colony formation, migration and invasion." (PMID 34804951, 2021). "When RBM10 expression is downregulated, Numb is also downregulated, which can lead to the activation of the Notch pathway, enhanced HeLa cell lines colony formation, and promotion of tumor growth and proliferation." (PMID 33718153, 2021). "Similar to these RBM proteins, RBM10 was recently shown by our group to act as tumor suppression." (PMID 32947864, 2020). "A549 cells infected with the GV358‐RBM10 lentivirus, causing overexpression of RBM10, or negative control cells were injected into nude mice and the tumour growth activity was measured." (PMID 30955253, 2019). "However, insufficient research has focused on RBM10‐related signalling pathways, which would explain the mechanism of its tumour‐suppressing effect." (PMID 30955253, 2019). "RBM10 is a tumor suppressor that represses Notch signaling and cell proliferation." (PMID 29156680, 2017). "In addition, it will be important to determine whether the tumor-specific exon inclusions mediated by RBM10 inactivation can serve as neoantigen-like targets for immunotherapies." (PMID 39874138, 2025). "Moreover, RBM10 level was substantially negatively associated with the MHC genes, chemokines, chemokine receptors, immune-stimulatory factors, and immunosuppressive factors in most tumor types." (PMID 39282149, 2022). "Most studies have proved that RBM10 may play a role in tumor progression." (PMID 39282149, 2022). "Therefore, we hypothesized that RBM10, as a tumor suppressor gene, may be involved in LUAD progression." (PMID 34975322, 2022). "However, other studies suggested that RBM10 might have a pro-cancer role as a tumor promoter or a pro-oncogene 9, 14-16." (PMID 34975322, 2022).